RN7SL146P (RNA, 7SL, cytoplasmic 146, pseudogene)
Gene: Miscellaneous RNA gene on chromosome 19 (16,539,688 to 16,539,984, reverse strand). Ensembl gene ENSG00000240106.
Homologues: Orthologues: chimpanzee Metazoa_SRP (99% identical), macaque Metazoa_SRP (84% identical). Paralogues in human: RN7SL1 (80% identical), RN7SL2 (79% identical), RN7SL3 (79% identical), RN7SL493P (78% identical), RN7SL709P (78% identical), RN7SL45P (77% identical), RN7SL679P (77% identical), RN7SL122P (77% identical), RN7SL481P (77% identical), RN7SL743P (77% identical), RN7SL769P (77% identical), RN7SL143P (76% identical), and 704 more.